IL1B (interleukin 1 beta)
Diseases named in the same sentence as IL1B in open-access papers (continued):
Sharing a sentence is not in itself a finding about the gene and the disease.
rheumatoid arthritis (continued). "For example, it has been reported that when synovial cells derived from rheumatoid arthritis patients were cultured on a material composed of a collagen-PVP composite, they exhibited suppressed expression of the inflammatory cytokines IL-1β and TNF-α50." (PMID 29674743, 2018). "miR-451 inhibits inflammatory cytokines secretion of TNF-α, IL-1β, and IL6 in human rheumatoid arthritis." (PMID 29652844, 2018). "Li and coworkers demonstrated that hesperidin decreased the production of IL-1β, IL-6, and TNF-α in a rat model of rheumatoid arthritis." (PMID 30347737, 2018). "GPI is closely related to the development of rheumatoid arthritis and is capable of stimulating the cytokine activity of TNF-α and IL-1β." (PMID 28384257, 2017). "Specifically, TAK1 expression has been observed in the synovial tissues of OA and rheumatoid arthritis (RA) patients, and TAK1 knockdown in rheumatoid arthritis-affected synoviocytes reduced matrix metalloproteinase-3 (MMP-3) expression by IL-1β." (PMID 28668088, 2017). "In addition, pioglitazone treatment modestly ameliorates rheumatoid arthritis (RA) activity by preventing bone loss and suppresses plasma levels of cytokines, including TNF-α, IL-1β, and IL-6." (PMID 27548145, 2016). "DFO treatment on LPS-stimulated microglia prevented the increase of TNF-α, IL-1β, and IL6, and these cytokines have been shown to increase iron uptake in human monocytes from patients with rheumatoid arthritis." (PMID 27733186, 2016). "Nevertheless, LU8C-FP failed to inhibit IL-1β and IL-8 expression, which provide information leading to the use of this flavonoid to treat inflammatory diseases caused by IL-6, such as colitis, diabetes, rheumatoid arthritis, cancer and cardiovascular diseases." (PMID 27294919, 2016). "On the other hand, ROS could be generated by rheumatoid synovial cells via the nicotinamide adenine dinucleotide phosphate (NADPH) oxidase system (Nox), during exposure to two major rheumatoid arthritis (RA) cytokines, interleukin-1β (IL-1β) and TNF-α." (PMID 26770659, 2016). "ICAM-1 can be induced by interleukin-1 (IL-1β) and TNF-α and is expressed by the A549 cells, human airway smooth muscle cells, or human rheumatoid arthritis synovial fibroblasts." (PMID 25675437, 2015). "In the synovial fibroblasts of patients with rheumatoid arthritis, IL-33 was detected and was markedly upregulated by the addition of TNF-α and IL-1β." (PMID 26557152, 2015). "Mechanistically, ciclamilast inhibited an increase in the expression level of IL-1β, IL-6, and TNF-α, leading to potential effects on both the acute and chronic phases in the treatment of rheumatoid arthritis." (PMID 26000303, 2015). "Recently, we also showed that IL-1β induced ICAM-1 expression via p42/p44 MAPK and JNK1/2 in human rheumatoid arthritis synovial fibroblasts." (PMID 25675437, 2015). "Treatment with an approved TNFα blocking antibody showed marked reduction in the levels of IL-6, IL-1β, and IL-17 and the expression level of STAT3 phosphorylation in relation to Th17 cell differentiation in patients with rheumatoid arthritis." (PMID 25436214, 2014). "We also performed an analysis of gene expression of the cytokines IL-1β and IL-6 and TNFα protein expression, since several studies have shown that inhibition of these cytokines may interfere with the degeneration of articular cartilage and subchondral bone in OA and rheumatoid arthritis." (PMID 24028507, 2013). "IL-6, LPS, IL-1β, IFN-α, IFN-γ and TNF-α induce CCAAT/enhancer-binding protein D (CEBPD) expression in rheumatoid arthritis." (PMID 23725043, 2013). "IL-1β and TNF-α are recognized contributors to the pathogenesis of joint diseases like rheumatoid arthritis (RA), thus leading to synovial fibroblast hyperplasia and the destruction of the extracellular matrix 8–10." (PMID 23331383, 2013). "It was reported previously that Th1 cytokines like IL-1β, TNF-α were higher in PsA compared to rheumatoid arthritis (RA)." (PMID 22417743, 2012).
rheumatoid arthritis (continued). "Synovial fibroblasts obtained from rheumatoid arthritis (RA) and osteoarthritis (OA) patients were stimulated with HMGB1 alone or in complex with LPS, IL-1α or IL-1β." (PMID 21871094, 2011). "IL-1β is a prototypical pro-inflammatory cytokine whose involvement in immuno-inflammatory diseases such as multiple sclerosis (MS) and rheumatoid arthritis (RA) is well established." (PMID 20686620, 2010). "Activation of p38α leads to the up-regulation of both TNFα and IL-1β, resulting in many chronic inflammatory diseases, such as rheumatoid arthritis (RA), inflammatory bowel disease, Crohn’s disease, and chronic obstructive pulmonary disease (COPD), as well as the other inflammatory disorders." (PMID 20957100, 2010). "ACZ885, a fully human monoclonal antibody that neutralizes the bioactivity of human IL-1β, was generated to study the potent and long-lasting neutralization of IL-1β in mechanistic animal models as well as in a proof-of-concept study in patients with rheumatoid arthritis (RA)." (PMID 18534016, 2008). "IL-1β increased the transcriptional and translational levels of MMP-1 and MMP-13 in rheumatoid arthritis FLSs, whereas the levels of MMP-2 and MMP-9 were unaffected." (PMID 17697361, 2007). "Recently, we reported that tumour necrosis factor (TNF)-α, IL-1α, IL-1β and IL-17 enhance Cyp7b mRNA expression and induce a concomitant increase in the formation of 7α-OH-DHEA by fibroblast-like synoviocytes (FLS) from rheumatoid arthritis patients." (PMID 16277680, 2005). "In osteoarthritis (OA) and rheumatoid arthritis (RA), the proinflammatory phenotype of the synovial macrophages (M1) is directly related to increased acetylation levels of the tumor necrosis factor α (TNF-α) and interleukin 1β (IL-1β) promoter regions." (PMID 41522338, 2026). "Both IL-1α and IL-1β bind to the IL-1 type 1 receptor (IL-1R1), inducing a wide range of secondary inflammatory mediators and playing critical roles in regulating immune and inflammatory processes, such as rheumatoid arthritis (RA) and systemic lupus erythematosus." (PMID 40371323, 2025). "In patients with OA, the immunoexpression levels of TNF-α, IL-1β, IL-7, MMP-1, MMP-2, and MMP-3 were significantly higher in patients with active rheumatoid arthritis (RA), whereas the immunoexpression levels of IL-1, IL-2, IL-4, IL-6, IL-15, IL-18, and MMP-3 were not statistically different." (PMID 40004793, 2025). "B lymphocytes in the peripheral blood of rheumatoid arthritis patients may release many cytokines, including TNF-α, IFN-γ, IL-6, IL-1β, IL-17, and IL-10, which facilitate bone deterioration." (PMID 41127878, 2025). "Recombinant IL-1RA is FDA approved for rheumatoid arthritis, in which IL-1β is increased two-fold in plasma and 100-fold in synovial fluid compared to individuals without rheumatoid arthritis." (PMID 41191631, 2025). "According to the ANDSystem knowledge base,interleukin-1 beta and the WNT5A protein mutually activateeach other’s expression, which may create a vicious cycle inthe pathogenesis of rheumatoid arthritis." (PMID 41536794, 2025). "Additionally, by activating the JNK signaling pathway, PSVII has been shown to suppress the expansion of fibroblasts in rheumatoid arthritis, alleviating symptoms and reducing levels of TNF-α, IL-6, and IL-1β." (PMID 40405066, 2025). "Moreover, prolactin induces the phosphorylation and activation of the signal transducer and activator of transcription-3 (STAT3), resulting in the downregulation of the osteoclast differentiation induced by proinflammatory cytokines, like IL-1β and IL-6, and rheumatoid arthritis (RA)." (PMID 38338751, 2024). "For example, stigmasterol treatment reduced TNF-α, IL-6, IL-1β, iNOS and COX-2 in collagen-induced rheumatoid arthritis (RA) rats, and increased the expression of anti-inflammatory cytokines (IL-10) by down-regulating NF-kB p65 and p38 MAPK expression in the joints." (PMID 38579176, 2024).
rheumatoid arthritis (continued). "While osteoarthritis is not typically classified as an inflammatory arthritis like rheumatoid arthritis, inflammatory cytokines such as IL-1β, IL-6, and TNFα play a role in its pathogenesis." (PMID 39769285, 2024). "Additionally, hesperidin was shown to reduce the production of IL-1β, IL-6, and TNF-β in a rat model of rheumatoid arthritis." (PMID 37020549, 2023). "Recombinant AREG upregulated the mRNA expression levels of vascular endothelial growth factor, IL-8, and IL-6, but not those of IL-1β or TNF-α in rheumatoid arthritis fibroblast-like synoviocytes." (PMID 37868614, 2023). "Lee and collaborators (2017) have shown that treatment with IL-1β and TNF-α raised CCR7 expression in both precursors and differentiated osteoclasts, increasing their migratory activity toward CCL19 and CCL21 chemokines upregulated in rheumatoid arthritis." (PMID 36831188, 2023). "In rheumatoid arthritis (RA), HOTAIR overexpression reduced the secretion of IL-23 and IL-17, and decreased the number of pro-inflammatory cells (Th17), as well as diminishing levels of IL-1β, phospho-p65, and TNF-α in cartilage." (PMID 37190068, 2023). "Interestingly, A20 deficiency in macrophages significantly enhanced NLRP3 inflammasome-mediated caspase-1 activation, pyroptosis, and IL-1β secretion, and negative regulation of the NLRP3 inflammasome by A20 protected against rheumatoid arthritis." (PMID 35794098, 2022). "In human synovial fibroblasts with rheumatoid arthritis, Tpl2 also induced ERK activation in the presence of IL-1β, whereas IL-1β stimulated the activation of ERK but also p38 MAPK signaling and JNK signaling in HeLa epithelial cell line or rat INS-1E β-cells, respectively." (PMID 34735542, 2021). "Finally, the anti-rheumatoid arthritis effects of the four target compounds were validated with the decreased levels of NO, TNF-α, IL-6 and IL-1β in RAW 264.7 macrophage cells treated with LPS." (PMID 34526896, 2021). "Cytokines TNF-α, IL-1β, IL-17, and transforming growth factor-β (TGF-β) levels were also significantly lowered after 10-days of treatment, and the effect was comparable with methotrexate, a drug used to treat rheumatoid arthritis." (PMID 33478498, 2021). "We show that the expression of IL-1β or IL-6 inducible transcriptional signatures (modules) reflects the bioactivity of these cytokines in immunopathology modelled by juvenile idiopathic arthritis (JIA) and rheumatoid arthritis." (PMID 33319166, 2021). "In addition, “bone inflammation disease” and “rheumatoid arthritis” ontologies were highly enriched in C3 regions, confirming that C3 regions represent an RA signature, for example, IL-1B and JAK1, which are essential for proinflammatory signal transduction and upregulated in RA patients." (PMID 33863328, 2021). "Besides, RSV is also known to reduce TNF-α-induced IL-1β and MMP-3 production by suppressing PI3K-Akt signaling in fibroblastoid synoviocytes of rheumatoid arthritis." (PMID 34497510, 2021). "It has been demonstrated that osteocytes are implicated in inflammatory diseases such as rheumatoid arthritis and may produce interleukin (IL)-1β, IL-6, and tumor necrosis factor-α (TNF-α) to mediate bone destruction in rheumatoid arthritis pathogenesis." (PMID 34093433, 2021). "In patients with rheumatoid arthritis, stimulation with IL-1β induced BMP-2 and BMP-6, but not BMP-4, BMP-5, or BMP-7 in fibroblast-like synoviocytes." (PMID 32290085, 2020). "For example, a study investigating bladder pain syndrome in Il1b–/– mice showed no improvement in bladder pathology and pain while studies in IL-1R–/– mice assessing gout and rheumatoid arthritis did not investigate pathology or pain improvement." (PMID 32973552, 2020). "Mangiferin downregulated TNF-α, IL-1β, and IFN-γ expression in TNF-α-stimulated CD3− synovial cells from rheumatoid arthritis (RA) patients, which indicated that mangiferin could be a potent candidate for the treatment of RA." (PMID 32019180, 2020).
rheumatoid arthritis (continued). "The proinflammatory cytokines such as IL-1β, IL-6, TNF, CXCL9, CXCL10, and IFN-γ participate in the pathology of several chronic inflammatory diseases including rheumatoid arthritis, coronary diseases, cerebral malaria, tegumentary leishmaniasis, and Chagas diseases." (PMID 32385802, 2020). "Also, in synovial fibroblasts from the temporomandibular joint of patients with rheumatoid arthritis, celecoxib reduced COX-2 and IL-6 expression by suppression of PG-E2 synthesis during stimulation of cells with PG-E2/IL-1β." (PMID 30983880, 2019). "In another study using a rheumatoid arthritis model of inflammation induced by LPS in vitro, hyperoside has demonstrated a significant (concentration-dependent) effect on inhibition of TNF-α, IL6 and IL-1β." (PMID 31405193, 2019). "Genistein was also shown to suppress the expression of IL-1β, IL-6, and TNF-α in the serum, which indicates that it could have the potential to improve symptoms of rheumatoid arthritis in rats." (PMID 31137797, 2019). "In clinical settings, inhibition of IL-1β through specific agonists or through IFN-β therapy is useful in limiting the development and progression of autoimmune and inflammation-mediated diseases, including rheumatoid arthritis and multiple sclerosis." (PMID 29559569, 2018). "In a rat model of rheumatoid arthritis, DPA showed a comparable reducing effect with EPA on the progression and severity of arthritic disease as well as pro-inflammatory cytokines, such as IL-17A, IL-1β, IL-6, and TNFα." (PMID 30347833, 2018). "Consequently, inhibition the production of IL-1β can reduce levels of these proinflammatory cytokine, and thereby reduce inflammation and prevent destruction effects in diseases such as rheumatoid arthritis (RA), osteoarthritis (OA) and Crohn’s disease." (PMID 28979306, 2017). "In rheumatoid arthritis, resistin has been shown to accumulate within inflamed joints, and to correlate with the degree of inflammation and the expression of inflammatory cytokines including TNF-α, IL-1β and IL-6." (PMID 28642544, 2017). "Another example of the role of cytokines in chronic diseases can be found between TNF-α and rheumatoid arthritis, where anti-TNF-α antibodies were added to in vitro cultures of cells from diseased joints and inhibited the production of IL-1β and other cytokines." (PMID 27294919, 2016). "Similar findings have been reported in that although tocilizumab treatment decreased TNF-α and IL-1β levels, serum IL-6 levels were increased by tocilizumab therapy regardless of the improvements in clinical measures in rheumatoid arthritis patients." (PMID 27068103, 2016). "Interestingly, when the concentration of 4-HNE increased to 50 μM, the mRNA levels of IL1-β, IL-6, and TNF-α in rheumatoid arthritis synovial cells increased gradually with the increasing time up to 1 h and then decreased." (PMID 25741130, 2015). "Accumulating evidences demonstrated that visfatin was identified as a proinflammatory adipocytokine and secreted extracellularly to upregulate inflammatory cytokines, such as TNF-α, IL-1β, IL-6 and CCL2 in rheumatoid arthritis synovial fibroblasts and monocytes in response to inflammatory stimuli." (PMID 25993304, 2015). "Especially in pre-existing osteoarthritis and in rheumatoid arthritis with abundant expression of TNF-α and IL-1β the use of FTY720 may accelerate cartilage degradation." (PMID 22151889, 2011). "In disorders such as rheumatoid arthritis (RA), osteoarthritis (OA), phlebitis, and IBD, GBP5 activates the NLRP3 inflammasome, thereby increasing IL-1β and IL-18 production, which exacerbates local inflammation (55, 138, –, 140)." (PMID 40788157, 2025). "In rheumatoid arthritis (RA), type III interferon can ameliorate joint inflammation by inhibiting the number of proinflammatory IL-17-producing Th17 and γδ T cells, as well as IL-1β-positive neutrophils in the joints and inguinal lymph nodes." (PMID 41359111, 2025).
rheumatoid arthritis (continued). "In rheumatoid arthritis (RA), patients exhibited reduced levels of AIM2 in their sera compared to healthy individuals, whereas levels of ASC, Caspase-1, and IL-1β are elevated." (PMID 39600708, 2024). "Notably, following the systemic administration of GRP78 or its analog IRL201805 in an animal model of rheumatoid arthritis, these proteins are rapidly internalized by monocytes, which eventually leads to an increased secretion of IL-10 and the suppression of TNF-α and IL-1β release." (PMID 38612761, 2024). "EA alleviates the inflammatory reaction by reducing the levels of serum pro-inflammatory cytokines such as IL-1, IL-1β, IL-6, IL-17, IL-23, and TNF-α in rheumatoid arthritis (RA) animal models and IL-17 in the peripheral blood of RA patients." (PMID 39335365, 2024). "TNFα, IL-1β, and hypoxia also up-regulate the expression of cytokines, including IL-6, CXCL8 (namely, IL-8), CCL2, CXCL11, CXCL12, and VEGF, as well as the expression of cytokine receptors such as TNFRSF9 in synovial fibroblasts derived from rheumatoid arthritis (RA) patients." (PMID 35967331, 2022). "Whilst the role of IL-6 may be secondary compared to IL-1β for the development of pathology in the K/BxN STIA model, its inhibition leads to therapeutic benefit in experimental and human rheumatoid arthritis, as both cytokines are key therapeutic targets to stop disease progression." (PMID 36505403, 2022). "For rheumatoid arthritis (RA), three JAK inhibitors and a range of bDMARDs are approved, including those targeting TNFα, IL-6, IL-1β, B cells (CD20), and T cells (CD80/CD86)." (PMID 34290741, 2021). "The pathophysiology of rheumatoid arthritis (RA) is characterized by excess production of pro-inflammatory cytokines, including tumor necrosis factor-α (TNF-α), interleukin-1β (IL-1β), and interleukin-6 (IL-6) by neutrophils and macrophages in synovium." (PMID 32131874, 2020). "Pro-inflammatory mediators contained with IL-1β, TNF-α, and PGE2 can also enhance the binding activity of NF-κB with Nurr1 promoter, thereby promoting Nurr1 transcription and elevating Nurr1 mRNA and protein level in primary rheumatoid arthritis and normal synoviocytes." (PMID 32477062, 2020). "Additionally, IL-1β treatment did not upregulate the production of CXCL16 by rheumatoid arthritis synovial tissue fibroblasts." (PMID 33552057, 2020). "Monocytes in the context of rheumatoid arthritis (RA) exhibit increased CPP uptake and IL-1β release in response to CaSR signaling." (PMID 32843625, 2020). "HS exerted treatment effects on RA by regulating 4 core targets (CSF2, IL1β, TNF, and IL6), which involved in 15 pathways such as rheumatoid arthritis, TNF signaling pathway, and cytokine-cytokine receptor interaction." (PMID 31885670, 2019). "Local ice cryotherapy significantly reduced the IL-6, IL-1β, VEGF, NF-kB-p65, and PG-E2 synovial levels, especially in the microcrystal-induced arthritis subgroup, while only phosphorylated NF-kB-p65 significantly decreased in rheumatoid arthritis and spondyloarthritis patients." (PMID 31362785, 2019). "However, another study found that caspase 1 expression was decreased in patients with rheumatoid arthritis, but the activity of caspase 1 was significantly increased, which only promotes the production of IL-18, not IL-1β." (PMID 31367484, 2019). "It has been reported that inflammatory cytokines such as IL-1β, IL-6 and TNF-α express in rheumatoid arthritis (RA) and induces osteoclastogenesis via increasing the expression of RANKL." (PMID 31763378, 2019). "Polyphenols reduce rheumatoid arthritis symptoms by regulating an extensive collection of RA-related molecules, including MAPK, IL-1β, IL-6, TNF-α, NF-κB, JNK, ERK1/2, AP-1 and COX-2." (PMID 31013659, 2019).